CD44 (CD44 molecule (IN blood group))
Diseases named in the same sentence as CD44 in open-access papers (continued):
Sharing a sentence is not in itself a finding about the gene and the disease.
breast carcinoma (continued). "Univariate analysis by Fisher’s exact test and Multivariate by logistic regression was employed to correlate the genotypes of the two CD44 polymorphisms with the clinicopathological features and breast cancer pathologic response to NACT." (PMID 23940692, 2013). "High levels of CD44 associated to low levels of CD24 (CD44(+)/CD24(-/low)) would characterize stem populations in breast cancer." (PMID 23976904, 2013). "In breast cancer the splice variant 4 of CD44 was shown as a major E-selectin ligand in facilitating tumor cell migration across endothelial monolayers." (PMID 24053443, 2013). "CD44 has been implicated in human breast cancer tumor progression, although little is known about the pathological role of CD44 in canine mammary tumors." (PMID 23426189, 2013). "In TICs isolated from primary breast cancer, shRNA-mediated knockdown of CD44 led to decreased expression of stemness-associated genes and to loss of tumorigenicity." (PMID 22901285, 2012). "It has been demonstrated that the interplay of adhesion molecule CD44 and its ligands can regulate cancer cell proliferation, migration and invasion, as well as tumor-associated angiogenesis and is related to breast cancer patient survival." (PMID 22788972, 2012). "Although CD44+/CD24- cells are believed to act as breast cancer stem cells and to be linked to poor prognosis in some patients, the association between these cells and tumor recurrence or metastasis in all or some types of invasive ductal carcinoma is unclear." (PMID 22762532, 2012). "Hyaluronan (HA) and the HA receptor CD44 have a long-standing association with cell invasion and metastasis of breast cancer." (PMID 22621373, 2012). "Previous studies have shown CD44 to be the hallmark of cancer stem cells in leukemia, pancreatic, and breast cancers." (PMID 22328825, 2012). "To determine if the tumor-initiating population of human breast cancer cells was enriched for reprogrammable cancer cells, we selectively isolated breast cancer cells with surface markers (CD44) associated with tumor-initiating activity." (PMID 23155468, 2012). "Previously SRSF5 expression has been shown to be increased in breast cancer, where it was associated with changes in alternative splicing of CD44 as well as lymph node metastasis." (PMID 23284704, 2012). "They report that the percentage of CD44+CD24lo cancer stem cells in the BM is higher in primary breast cancer patients with high risk tumor features." (PMID 22264265, 2012). "Our studies thus provide a new molecular insight to substantiate the association of CD44 with the metastasis of breast cancer." (PMID 22621373, 2012). "In this study, five eligible tag single nucleotide polymorphisms (tagSNPs) of CD44 gene were selected from the Genbank dbSNP database to evaluate the contribution of detected polymorphisms to risk of developing breast cancer." (PMID 22788972, 2012). "For example, whilst HA stimulation of CD44s is suggested to mediate breast cancer cell adhesion, motility and invasion, HA stimulation of CD44 variants regulate only cell motility." (PMID 23039365, 2012). "Our study indicated that compared with the CD44 rs13347 CC genotype, the variant genotypes (CT+TT) can elevate the risk of breast cancer and predicts poorer five-year survival rate in both Southern and Eastern Chinese populations." (PMID 22788972, 2012). "CD44 variant 4 (CD44v4), among the multiple variants of common E-selectin ligand CD44, has been identified as a major E-selectin ligand for breast cancer cells." (PMID 22866263, 2012). "To confirm the results of Western blotting, we further performed the IHC study in 31 breast cancer tissues to verify association between expression level of CD44 protein and rs13347C >T in vivo." (PMID 22788972, 2012). "In many cancer types, including breast cancer, CD44 and some of its alternate splice variants have been associated with increased invasion, metastasis and with poor prognosis." (PMID 22937154, 2012).
breast carcinoma (continued). "Our data identified HIF-1α as a regulator of CD44 that increased the number of CD44 molecules and the percentage of CD44 positive cells expressing variant exons v6 and v7/8 in breast cancer cells under hypoxic conditions." (PMID 22937154, 2012). "Together, our observations on human breast cancer clinical samples confirm the relevance of previous in vitro/in vivo studies and underline the utility of a careful evaluation of the CD44+/CD24− population in naive primary human tumours." (PMID 23028444, 2012). "Breast cancer stem cells, identified on the basis of CD44+CD24-/low expression, are associated with metastases and drug resistance." (PMID 23046710, 2012). "CD44 knockout in mouse breast cancer model caused increased numbers of lung metastases, which correlated with reduced invasion of CD44-expressing metastatic breast cancer cell lines into HA-containing collagen matrixes." (PMID 22216242, 2011). "More pronounced cytotoxic effects were observed when HA was conjugated to paclitaxel on CD44-overexpressing breast cancer cells compared to CD44-deficient cells, suggesting that HA-conjugation can be potentially utilized as tumor-targeted therapy." (PMID 21541039, 2011). "Presence of CD44+/CD24- tumor cells has also been associated with the aggressive basal-like molecular subtype of breast cancer." (PMID 21957977, 2011). "In univariate analysis, CD44+CD24-/low expression showed association with death due to breast cancer (p = 0.035)." (PMID 21824412, 2011). "We aimed to investigate potential associations between alternatively spliced isoforms of CD44 and CSCs as well as to various breast cancer biomarkers and molecular subtypes." (PMID 21957977, 2011). "Overexpression of soluble forms of CD44 inhibits HA-adhesion of mouse mammary carcinoma or melanoma cells and caused inhibition of tumor cell proliferation, and reduced tumorigenicity." (PMID 22216242, 2011). "It was reported that basal-like and BRCA1-associated breast carcinomas, which are also related were both enriched with CD44+/CD24− candidate stem cells, and BRCA1 has been suggested to represent a stem cell regulator." (PMID 20010944, 2010). "Recent experimental and clinical investigations showed that CD44 together with heparanase and hyaluronan regulates tumour cell proliferation, migration, invasion and angiogenesis and associates with breast cancer patient survival." (PMID 20565761, 2010). "In contrast, cytotoxic chemotherapies including Dox increased the proportion of CD44/CD24- breast cancer cells and mammosphere-forming activity associated with a significant antitumor activity in HER2-negative breast cancers." (PMID 20959018, 2010). "Using either CD44+/CD24- or CD133+ cells isolated from Brca1-deficient mouse mammary tumors, expression of Sox1 was found to be significantly higher in these cells when compared to their counterparts." (PMID 20929579, 2010). "The fact that P245 treatment during tumour remission inhibits tumour recurrence suggests that CD44+ cells play a direct role in the tumour recurrence, providing an interesting target and a useful model to finalise breast cancer therapies associations." (PMID 19240712, 2009). "Although its precise role has remained unclear, CD44 has been amply associated with breast cancer pathogenesis." (PMID 19602265, 2009). "Is the CD44+/CD24low/- phenotype associated with CSCs only in certain breast cancers, predominantly basal-like or BRCA1?" (PMID 19555472, 2009). "Here, for the first time, our results demonstrate that CD44v4 is a major CD44 isoform expressed in metastatic breast cancer cells, and this CD44 variant is a membrane glycoprotein decorated with E-selectin binding sLex moieties." (PMID 18350162, 2008). "A recent study by Shipitsin and coworkers implicated that CD24+ and CD44+ cells within breast carcinomas represent defined cell populations with distinct genetic profiles." (PMID 18559090, 2008).
breast carcinoma (continued). "To solve this problem, we amplified the cDNA encoding the CD44 extracellular domain from various breast cancer cells using a pair of primers, forward primer 5′-TATAAGCTTTTCGCTCCGGACACCATGGACAAG-3′, and reverse primer 5′-ATAAGATCT TTCTGGAATTTGGGGTGTCCTTAT-3′." (PMID 18350162, 2008). "In the present study, we demonstrated that metastatic breast cancer cells strongly express a ∼170 kD CD44 variant 4 (CD44v4)." (PMID 18350162, 2008). "Recently, CD44+CD24-/low lineage-cells were implicated in breast cancer initiated tumorigenesis in NOD/SCID mice." (PMID 18433506, 2008). "We found that CD44+/CD24- Brca1-deficient mouse mammary tumor cells have cancer stem cell characteristics in vitro, and 50 of these cells are sufficient to initiate tumors in mice." (PMID 18241344, 2008). "Brca1-deficient mouse mammary tumors harbor heterogeneous cancer stem cell populations, and CD44+/CD24- cells also identify human breast cancer stem cells." (PMID 18241344, 2008). "CD44 associates with a proteolytic form of the matrix metalloproteinase-9 (MMP-9) on the surface of mouse mammary carcinoma and human melanoma cells." (PMID 17343740, 2007). "Surface association of CD44 with MMP-9 was shown to provide a mechanism for tumor invasion in mouse mammary carcinoma and human melanoma cells." (PMID 17343740, 2007). "In tamoxifen-resistant breast cancer, cs78 binds to a variant form of CD44 on the cell surface and stabilizes it, as treatment with antibodies against GRP78 reduces cell surface CD44 protein levels, leading to F-actin disorganization and loss of cell attachment and spreading." (PMID 40699920, 2025). "Moreover, kynureninase associated with the onset and development of breast cancer was found to be upregulated by CD44, which was induced and activated by HA." (PMID 38783892, 2024). "In addition, a study indicated that CD44(+)/CD24(−/low) breast cancer stem-like cells play a pivotal role associated with the clinical behavior of triple-negative breast cancer." (PMID 38392969, 2024). "Furthermore, in breast cancer brain metastases patients, a retrospective transversal study revealed that CD44 was associated with worse overall survival." (PMID 38783892, 2024). "Another study demonstrated that TDP-43 might enhance the stemness of breast cancer stem cells through alternative splicing of the CD44 variant (CD44v)." (PMID 38281298, 2024). "In mammary cancer cells, prolactin causes elevation of intracellular ferrous iron pools (also known as labile iron pools) through the upregulation of the surface receptor CD44." (PMID 39201626, 2024). "It was found that there were significant differences between different subtypes of CD44 that affected the biological behavior of breast cancer cells, among which the subtypes associated with breast cancer invasion, metastasis, and patient prognosis mainly included CD44s, CD44st, CD44v6, and CD44v9." (PMID 36964570, 2023). "Breast cancer treatment frequently has favorable results when compared to other types of early‐stage cancer treatment, making this initial identification critical, and CD44 is the diagnostic target in the early stages of the disease." (PMID 36289579, 2023). "CD44, as a tumor‐associated marker, can be used to detect stem cells in breast cancer." (PMID 36289579, 2023). "Also, overexpression of CD44 variable isoforms (CD44v) is associated with malignancy in breast cancer." (PMID 36759786, 2023). "It was also able to reduce the expression of c-Myc, Sox-2, and Oct4, which are stemness-associated proteins, in breast cancer cells and to decrease the proportion of CD44+/CD24− breast cancer stem cells in the tumor population, thus inhibiting tumor progression." (PMID 37894640, 2023). "Besides, high expression of CD44 in breast cancer has been associated with improved survival after neoadjuvant chemotherapy treatment." (PMID 38124067, 2023).
breast carcinoma (continued). "Next, we investigated other potential determinants of TNBC aggressiveness exploring the self-renewal capability of the mammosphere-forming MDA-MB-231 cells, which are acknowledged to exhibit certain features associated with mammary cancer stem cells (CSCs) like the CD44+/high/CD24−/low phenotype." (PMID 37749101, 2023). "A recent study showed that CD44 isoform switching from expressing CD44v to CD44s was essential for epithelial to mesenchymal transition (EMT) during breast cancer progression; whereas, CD44 variants are reported to be associated with metastatic lesions and with a poor prognosis." (PMID 35931675, 2022). "Activation of SDF-1/CXCR4 signalling may increase the phosphorylation of 60 proteins associated with the migration and invasion of CD44+CD24− CSCs in breast cancer." (PMID 35563449, 2022). "MMP-9 has been shown to be associated with CD44 on breast cancer cells and human melanoma cells." (PMID 35264209, 2022). "Recently, CD44 has also been found to be preferentially loaded into cancer-derived exosomes and has been implicated in driving chemoresistance in a model of doxorubicin-treated breast cancer." (PMID 35257663, 2022). "Hence, a higher frequency of CD44-/CD24- breast cancer cells, like higher frequency of CD44+/CD24- CSCs, was associated significantly with a shorter DFS in the training set of patients regardless of standard therapies." (PMID 34318746, 2021). "Expression of CD44 on EVs has been associated with breast cancer recurrence." (PMID 34571870, 2021). "Moreover, an analysis of human breast cancer tissues demonstrated that greater CD44 expression is linked to a higher histological tumour grade." (PMID 34944493, 2021). "Moreover, activation of ERK-MAPK signaling leads to translocation of SMAR1 to the cytoplasm, resulting in increased CD44 variants alternative splicing and metastasis in breast cancer cells." (PMID 33863392, 2021). "Thus, a higher frequency of CD44-/CD24- tumor cells was associated with worse survival of breast cancer patients following standard therapies." (PMID 34318746, 2021). "The hyperactivation of the PI3K/AKT pathway has also been linked with the induction of EMT in human mammary cancer cells and the upregulation of PD-L1, in addition to the expression of a well-known stem cell marker: the cluster of differentiation 44 (CD44) molecule." (PMID 33506060, 2021). "Furthermore, TQ was found to significantly decrease breast cancer-associated stem cell clone (CD44+/CD24-cell) in both MCF-7 and T47D cells." (PMID 31968657, 2020). "CD44+/CD24- has been associated with breast cancer resistance to ionizing radiation." (PMID 33680952, 2020). "Thus, CD44 is associated with breast-cancer progression: cell adhesion, behavior, motility, morphology, and tumorigenesis." (PMID 32316333, 2020). "Furthermore, we assessed the breast cancer-associated stem cell clone (CD44+/CD24-) and endothelial mesenchymal transition gene expression in relation to treatment with TQ, PTX, and their combination." (PMID 31968657, 2020). "Although HA and CD44 have been linked to inflammation, whether the HA-CD44 axis directly drives the expression of inflammatory mediators in breast cancer cells remains understudied." (PMID 32455980, 2020). "For example, a high CD44 expression was a poor prognostic factor for breast carcinoma, lymphoma and thymoma, while, in other studies, a loss/reduced CD44 expression was correlated to a poorer prognosis, such as carcinoid tumour, gastrointestinal stroma tumour, laryngeal carcinoma and lung carcinoma." (PMID 32961774, 2020). "Similarly, our results showed that the CD44+/CD24–/low BCSCs from HER2-negative breast cancer cells were associated with HER2 and EGFR overexpression and the radioresistant phenotype." (PMID 29464036, 2018). "There are few studies reporting the association between CD44 polymorphisms and breast cancer risk." (PMID 29483847, 2018).
breast carcinoma (continued). "In addition, TQ, GCB and their combination depleted breast cancer associated stem cell (CD44(+)/CD24(−)/(low)) clone within MCF-7 and T47D cells by 3.8% to 27.5%." (PMID 30076320, 2018). "HA activation of CD44 caused an activation of c-Src in breast cancer cells." (PMID 29747682, 2018). "CD44 or CD44-like receptors are significantly over-expressed in different solid tumors, including lung cancer, pancreatic cancer, and breast cancer, thus, tremendous efforts have been focused on studying the diagnostic and prognostic value of CD44, and particularly CD44v isoforms, in cancer." (PMID 30544868, 2018). "CD44 is a transmembrane glycoprotein that is associated with breast cancer metastasis." (PMID 30171384, 2018). "To further explore this drug-induced change in CSC character, we employed a commercially available antibody to assess levels of CD44v6, a CSC-associated isoform of CD44 that promotes tumor cell motility and is correlated with poor prognosis in breast cancer patients." (PMID 29928062, 2018). "Therefore, the current study aimed at investigating the association between specific polymorphisms in exon 2 and its flanking region of CD44 with predisposition to breast cancer." (PMID 29483847, 2018). "However, the association of a CD44+/CD24−/low population with the clinical outcome of patients with breast cancer and drug resistance, particularly to specific types of chemotherapeutics, is unclear." (PMID 28418843, 2017). "In breast cancer, a significant increase in CD44 and its variants has been found in malignant and premalignant lesions compared to normal breast tissue providing further confirmatory evidence to the role of CD44 in the development of distal metastasis and tumor progression." (PMID 28609459, 2017). "It was suggested that an increase in micro vessel number and expression of CD44 might be useful diagnostic markers of metastasis of breast cancer." (PMID 28326306, 2017). "Given the association of CD44 with tumor progression, we hypothesized that its overexpression may act to promote the aggressive behavior of endocrine-resistant breast cancers." (PMID 27379207, 2016). "This poses the question of whether individuals with breast cancer and synchronous chronic inflammation who have elevated sE-selectin and CD44+ circulating tumor cells (CTCs) are predisposed to increased risk of organ metastasis." (PMID 27220365, 2016). "Furthermore, Asp-UA (80 mg/kg) reduced lung metastasis in a 4T1 murine breast cancer metastasis model more efficiently, which was associated with a decrease in the expression of CD44." (PMID 27683033, 2016). "However, the association of CD44+/CD24−/low population with clinical outcome of patients with breast cancer is unclear." (PMID 26444008, 2015). "Furthermore, HA association with CD44 was suggested to induce Twist expression following CD44 nuclear translocation and activation of the lysyl oxidase promoter in human breast cancer." (PMID 26322272, 2015). "Therefore, our studies support that elevated CD44 expression can predict an increased risk of distant metastasis and reduced disease-free survival in discrete sub-populations of breast cancer patients." (PMID 25888636, 2015). "Because CD44 is associated with breast cancer cell invasion, we want to determine whether activation of CD44 is essential for the oncogenic and invasive properties of AF1q." (PMID 26079538, 2015). "To determine whether the CD44 expression pattern is altered in these four breast cancer cell lines compared with the four normal cells, we next determined the expression of CD44 variants." (PMID 25909172, 2015). "We submit that further studies into mechanisms underlying the regulation of CD44 palmitoylation and lipid raft containment may merit evaluation as a novel target to reduce breast cancer metastatic spread." (PMID 24512624, 2014).